EGFR (epidermal growth factor receptor)
Diseases named in the same sentence as EGFR in open-access papers (continued):
Sharing a sentence is not in itself a finding about the gene and the disease.
squamous cell carcinoma (continued). "The mouse monoclonal antibody (MAb) 225 was identified in 1983 as a potent inhibitor of EGF binding to EGFR, resulting in a significant decrease in proliferation of A431 epidermoid carcinoma cells displaying EGFR amplification." (PMID 27153091, 2016). "We observed squamous cell carcinoma patients had significantly shorter DFS and OS than those with adenocarcinomas, especially in the context of EGFR mutations, consistent with previous reports." (PMID 27072585, 2016). "Studies have showed that AF inhibited EGF binding to HeLa cells and enhanced protein kinase C-mediated EGFR phosphorylation in epidermoid carcinoma cell line." (PMID 27846303, 2016). "When subdivided according to the histological type of tissue, EGFR positivity was found to be 47.9% in squamous cell carcinomas and 38.2% in adenocarcinomas." (PMID 27438047, 2016). "In recent years, brain metastasis are increasingly seen in adenocarcinomas with epidermal growth factor receptor (EGFR) mutations and EML4ALK1 rearrangement, whereas squamous cell carcinomas in many cases have a tendency to locally invade the thoracic wall." (PMID 27018053, 2016). "Third, this study included 5 patients with squamous cell carcinoma, they all received EGFR-TKIs monotherapy." (PMID 26624882, 2016). "If HeLa cells have about 3–4 × 105 receptor molecules on PM which become saturated at EGF concentration of about 4 nM, the human epidermoid carcinoma cell line A431 possesses about 2–3 × 106 EGFR per cell which become saturated at about 25–30 nM of EGF." (PMID 26716513, 2016). "Ligand-independent EGFR activation acts as a survival signal in squamous cell carcinoma that can trigger phosphatidylinositol 3′-kinase- (PI3K-) mediated AKT activation." (PMID 27313893, 2016). "Apart from that, inhibition of the EGFR is able to induce the formation of desmosomes and promote cell adhesion in squamous cell cancer cells." (PMID 27428951, 2016). "We noted that squamous cell carcinoma had a significantly higher proportion of EGFR overexpression (82.1%) compared to other subtypes (p = 0.002)." (PMID 26115045, 2015). "This level was an order of magnitude lower as compared to A431 epidermoid carcinoma cells known for high EGFR expression." (PMID 26465157, 2015). "Further analysis to correlate EGFR expression with MFI showed a strong correlation of squamous cell carcinoma (SCC) with EGFR expression." (PMID 26120042, 2015). "We chose the epidermoid carcinoma cell line A431, which overexpresses wild type epidermal growth factor receptor (EGFR), as a developmental platform." (PMID 26112401, 2015). "Squamous cell carcinomas had a significantly higher proportion of EGFR overexpression (82.1%), compared to other subtypes (p = 0.002)." (PMID 26115045, 2015). "Al-Nedawi and colleagues reported that exosome-derived oncogenic EGFR from human squamous cell carcinoma activated, in endothelial cells, MAPK and Akt cell signaling pathways, promoting VEGF expression." (PMID 25644060, 2015). "In squamous carcinoma the EGFR gene amplification and the cross-talk between other members of the HER family have been implicated in oncogene-driven processes." (PMID 26402860, 2015). "An epidermoid carcinoma cell line (A431) was used as the positive control as these cells are known to overexpress EGFR." (PMID 25918252, 2015). "In squamous carcinoma, the EGFR gene amplification, the cross-talk between other members of the HER family and the interaction with viral proteins have been implicated in oncogene-driven processes and remain an active subject of investigation." (PMID 26402860, 2015). "EGFR overexpression in this study was found in 71 (47%) of 151 never-smokers and was more frequent in adenocarcinoma (56%) than in squamous cell carcinoma (34%); results which were consistent with previous reports." (PMID 25806093, 2015). "PLCγ1 is required for the epidermal growth factor receptor (EGFR)-induced squamous cell carcinoma cell mitogenesis." (PMID 26633375, 2015).
squamous cell carcinoma (continued). "Ruohong Shui and collegues reported three cases of primary squamous cell carcinoma of the breast with an unusual “basal-HER2” phenotype This tumor overexpresses usually the Epiderml Growth Factor Receptor EGFR." (PMID 27386028, 2015). "A high-throughput genotyping platform showed that squamous cell carcinoma and adenocarcinoma have distinct molecular profiles; KRAS mutations were identified only in adenocarcinoma and EGFR mutation was detected only in squamous cell carcinoma." (PMID 26660311, 2015). "In experiments using the A431 human squamous cell carcinoma xenografted model which over-expresses EGFR, HER2 and HER3, the anti-tumor effects were seen with an average tumor growth delay of 21 days at doses as low as 1.2 mg/kg." (PMID 25110867, 2014). "The combination of cetuximab and radiotherapy (CRT) has also been tested in several other EGFR-expressing squamous cell carcinomas including lung, anal, esophageal, and uterine cervix squamous cell carcinoma." (PMID 25136458, 2014). "Altogether, expressions of p16INKA4, EGFR and its phosphorylated form pEGFR have been proposed to reflect infection with high risk HPV in squamous cell carcinoma of conjunctiva." (PMID 24572046, 2014). "In squamous cell carcinoma and brain tumors, epidermal growth factor receptor (EGFR) and its mutant form EGFRvIII also regulate the expression of flTF, FVII, protease-activated receptor 1 (PAR1) and PAR2." (PMID 25084809, 2014). "EGFR, a transmembrane tyrosine kinase, has been shown to be upregulated in a variety of squamous cell carcinomas and its downstream antiapoptotic signaling cascade has been well studied." (PMID 25136458, 2014). "The HCC95 cell line is derived from squamous cell carcinoma with wild-type (wt) EGFR and an IC50 value of > 10 μM for Gefitinib." (PMID 25375092, 2014). "While increased EGFR expression has been observed in vocal fold squamous cell carcinoma and benign vocal fold disorders, EGFR expression in vocal fold epithelium following injury has not been examined." (PMID 25514022, 2014). "Many cancers have up-regulated epidermal growth factor receptor (EGFr), so we have used antibodies to this receptor (ErbituxTM), and A431 human squamous cell carcinoma cells and tumors which overexpress EGFr." (PMID 24520385, 2014). "Dacomitinib irreversibly inhibited EGFR autophosphorylation in the A431 squamous cell carcinoma cell line with IC50 of 15.1 nmol/L alone or in the presence of EGF." (PMID 25110867, 2014). "EGF-induced EGFR activation in human epidermoid carcinoma A431 cells was shown to be strongly inhibited by GM3, but to a much lesser degree by various other gangliosides and neutral GSLs." (PMID 24944646, 2014). "For comparative study, the efficacy of DBDx and gefitinib was evaluated with the human epidermoid carcinoma A431 xenograft model in which EGFR is highly-expressed." (PMID 25531414, 2014). "There were 67 patients with primary squamous cell carcinoma of the head and neck in this cohort who met inclusion criteria and for whom we had complete E-cadherin, beta-catenin and EGFR expression data." (PMID 24722213, 2014). "In vitro cell uptake studies showed up to 90% internalization of the EGFR-targeted Ni-LNPs into the EGFR overexpressing A431 human epidermoid carcinoma cells, while a significantly lower uptake (10%) was observed with untargeted Ni-LNPs." (PMID 24564841, 2013). "Systemic delivery of decorin protein core, downregulated the epidermal growth factor receptor (EGFR), leading to growth inhibition as well as increased apoptosis of squamous cell carcinoma xenografts in mice." (PMID 24499526, 2013).
squamous cell carcinoma (continued). "It has been shown that extracellular Hsp70 released from heat-stressed A431 squamous carcinoma cells triggers autocrine epidermal growth factor receptor (EGFR) and MAPK signaling via TLR2/4." (PMID 24362507, 2013). "α5β1 was also observed to simultaneously control EGFR-dependent proliferation and Akt-dependent pro-survival signaling in epidermoid carcinoma cells." (PMID 24130778, 2013). "The cellular model for the tumor cells with increased receptor synthesis was chosen to resemble the characteristics of A431 cells, a human squamous carcinoma cell line with high EGFR levels." (PMID 22399130, 2012). "A431, an epidermoid carcinoma cell line, was used as a positive control for EGFR expression in most studies, since it has been reported to express high levels of EGFR." (PMID 22922885, 2012). "To delineate distinctive role of the components of α5β1 integrin-EGFR axis in control of epidermoid carcinoma cell proliferation, we performed individual inhibition of α5β1 and EGFR via genetic and phamacological methods, respectively." (PMID 22626691, 2012). "Binding, internalization, nuclear translocation and cytotoxicity were evaluated using two EGFR-expressing human cancer cell lines - A431 epidermoid carcinoma cells and D247 MG malignant glioma cells, which express varying levels of EGFR." (PMID 23107475, 2012). "In squamous cell carcinoma of the head and neck, monoclonal antibodies directed against EGFR have become a regular component of therapy for curative as well as palliative treatment strategies." (PMID 23150825, 2012). "As a positive control, anti-EGFR antibody binding of the EGFR-overexpressing human epidermoid carcinoma A431 cell line was used for this assay." (PMID 22374986, 2012). "The Epidermal Growth Factor Receptor (EGFR) is overexpressed in the vast majority of cases of Squamous Cell Carcinoma of the Head and Neck (SCCHN)." (PMID 22745915, 2012). "Whilst improvements in PFS were seen in both adenocarcinoma and squamous cell carcinoma, the magnitude of improvement in PFS was significantly greater in those with EGFR mutation (45 vs. 13 weeks)." (PMID 29147317, 2012). "Clinical studies of the effectiveness oftargeted drugs (erlotinib, gefitinib, cetuximab), applied in combination withchemoradiation therapy against squamous-cell carcinoma of the head and neck with amutation in the EGFR gene, continue around the world." (PMID 22708067, 2012). "In particular, overexpression and amplification of the EGFR is present in 80–100% of squamous cell carcinomas of the head and neck and portends poor prognosis, inferior survival, radioresistance, and treatment failures." (PMID 21912620, 2011). "To explore how different ligand concentrations affect the activation of EGFR-dependent signaling pathways, we stimulated serum-starved A431 epidermoid carcinoma cells for five minutes with twelve concentrations of EGF, ranging from 250 pM to 32 nM." (PMID 21264347, 2011). "Amplification of EGFR was more frequently found in cells of squamous cell carcinomas than in cells of adenocarcinomas/adenosquamous cell carcinomas (P<0.05, χ2-test)." (PMID 21730982, 2011). "The higher frequency of EGFR expression in squamous cell carcinomas compared with adenocarcinomas/adenosquamous cell carcinomas is a finding of interest." (PMID 21730982, 2011). "This was observed in studies of squamous carcinoma cells (T-Hep3) that naturally overexpress the uPA receptor, one of which found that EGFR was activated by the uPA receptor in a ligand-independent fashion, resulting in resistance to EGFR mAb." (PMID 21822357, 2011).
squamous cell carcinoma (continued). "Treatment for squamous cell carcinoma of the head and neck has significantly improved with the addition of cetuximab, a monoclonal antibody against the epidermal growth factor receptor, to conventional cytotoxic agents." (PMID 21951623, 2011). "High EGFR staining intensity (2+ and 3+) was more frequently found in cells of squamous cell carcinomas than in adenocarcinomas/adenosquamous cell carcinomas (P<0.0001, χ2-test)." (PMID 21730982, 2011). "Though EGFR was most commonly found in squamous cell (70%) followed by adenocarcinoma (50%), and large cell carcinomas, in our study, EGFR positivity rates were similar between squamous carcinoma (40%) and adenocarcinorma (50%)." (PMID 21385353, 2011). "In human squamous cell carcinoma, the activation of EGFR stimulates TF expression, which is modulated by E-cadherin in vitro, and an E-cadherin-neutralizing antibody led to the upregulation of TF expression." (PMID 21245964, 2011). "In a phase III trial, adding cetuximab, an EGFR inhibitor, to RT provided improvement in locoregional control and overall survival on squamous cell carcinoma of the head and neck." (PMID 20470428, 2010). "In the present study, four tonsil squamous cell carcinomas showed EGFR gene amplification, defined as a ratio of EGFR gene copies to CEP7 gene copies of at least two in more than 10% of tumour cells." (PMID 20459770, 2010). "In a recent manuscript, we have demonstrated similar inhibition of EGFR function by lovastatin in squamous cell carcinoma cells." (PMID 20838437, 2010). "The aim of the present study was to analyse EGFR expression, EGFR gene copy number and EGFR and K-RAS mutational status in formalin-fixed, paraffin-embedded specimens from two cohorts of patients with squamous cell carcinoma, anal canal and tonsils." (PMID 20459770, 2010). "Summary of Epidermal Growth Factor Receptor expression in anal canal and tonsil squamous cell carcinoma." (PMID 20459770, 2010). "EGFR immunoreactivity was present in 36/43 (83.7%) of anal canal and in 20/24 (83.3%) of tonsil squamous cell carcinomas." (PMID 20459770, 2010). "The aim of this study was to analyse EGFR expression, EGFR gene copy number and EGFR and K-RAS mutations in two cohorts of squamous cell carcinomas, specifically anal canal and tonsil carcinomas." (PMID 20459770, 2010). "Abundant preclinical and clinical data suggest that blocking the function of EGFR can enhance the efficacy of chemotherapy and radiotherapy and promote tumor regression in epithelial and squamous carcinomas." (PMID 20498858, 2010). "In our investigated panel, only one mutation in the K-RAS gene of a tonsil squamous cell carcinoma was identified, indicating that EGFR and K-RAS mutations are infrequent in this cohort of squamous cell carcinomas." (PMID 20459770, 2010). "In head and neck cancer, EGFR exons 18 to 21 were screened by HRM, resulting in the detection of two EGFR mutations in 24 squamous cell carcinomas." (PMID 18495026, 2008). "Recent evidence suggests superiority of the EGFR inhibitor (EGFRI) cetuximab plus radiotherapy compared to radiotherapy alone in patients with squamous cell carcinoma of the head and neck." (PMID 18226196, 2008). "Then, the behaviors of uPAR down-regulated cells were compared with NA-SCC squamous carcinoma cells showing similar uPAR/EGFR expression profile." (PMID 18519000, 2008). "Jimeno and co-workers demonstrated that the combination of temsirolimus and erlotinib results in a synergistic antitumour effect against squamous cell carcinoma cell lines, sensitive or resistant to EGFR inhibitors." (PMID 18319715, 2008). "The epidermal growth factor receptor (EGFR) is a validated target in squamous cell carcinoma (SCC) of the head and neck." (PMID 17342092, 2007).
squamous cell carcinoma (continued). "The results from phase II trials of gefitinib in advanced recurrent NSCLC indicate that response seems to occur more frequently in patients with adenocarcinoma than with squamous carcinoma, but this observation requires confirmation with other EGFR inhibitors." (PMID 15150574, 2004). "Although high EGFR expression was more common in squamous-cell carcinomas than adenocarcinomas, all objective responses were observed in patients with adenocarcinoma." (PMID 15187994, 2004). "The study panel of human squamous cell carcinoma cells showed substantial variability in EGFR expression, ranging from 388 (Hep-2) to 33 794 (CAL33) fmol per mg cell protein." (PMID 11875748, 2002). "The assessment of EGFR content confirmed that EGFR expression varied substantially between cell lines in the panel of head and neck human squamous cell carcinoma cells." (PMID 11986789, 2002). "The expression of EGFR was higher in squamous cell carcinomas whereas the level of p185HER-2 staining was higher in adenocarcinomas." (PMID 8679464, 1996). "The purpose of this study was to determine the effect of the first rat monoclonal antibody (MAb ICR62) to the epidermal growth factor receptor (EGFR) in a phase I clinical trial in patients with unresectable squamous cell carcinomas." (PMID 8546911, 1996). "Staining for EGFr in 40 squamous carcinomas was significantly stronger than in 37 specimens of other types of NSCLC (P less than 0.05), and staining in stage three NSCLC was stronger than in stage 1 and 2 (P less than 0.05)." (PMID 3038157, 1987). "Moreover, the EGFR associates with the Na+-dependent neutral amino acid transporter ASCT2 in squamous cell carcinoma cells, while EGFR inhibition suppresses glutamine uptake." (PMID 39433211, 2025). "Additionally, LIPTAC1 efficiently degraded EGFR with a maximal percent degradation (Dmax) of 86%, on the EGFR high expressing epidermoid carcinoma cell line A431." (PMID 40661577, 2025). "When stratified by histologic subtype, EGFR mutations were significantly more frequent in non-squamous tumors (19.1%) than in squamous cell carcinomas (6.5%)." (PMID 41465119, 2025). "Finally, about 2–15% of patients treated with EGFR-TKIs develop a histological transformation from adenocarcinoma to small cell lung cancer (SCLC), or rarely to squamous carcinoma, acquiring resistance to EGFR-TKIs." (PMID 40361442, 2025). "Similarly, preclinical combination studies of alpelisib and cetuximab inhibited EGFR phosphorylation, resulting in inhibition of mTOR activation and subsequent cell death in squamous cell carcinoma cells and tumors." (PMID 40161411, 2025). "Baseline characteristics were well-balanced between the EAP and non-EAP cohorts, except for a higher proportion of squamous cell carcinoma histology and wild-type EGFR mutation in the non-EAP cohort." (PMID 41199831, 2025). "Importantly, Gamou and Shimizu were the first to demonstrate that treatment of human squamous carcinoma cells with hydrogen peroxide enhances EGFR phosphorylation, thereby establishing a link between oxidative stress and EGFR activation." (PMID 41145430, 2025). "The diagnosis by gastroscopic biopsy was squamous cell carcinoma (SCC) with EGFR over-expression." (PMID 38606154, 2024). "Notably, a shorter overall survival (OS) has been evidenced in patients of early or advanced CC with mutant KRAS and PIK3CA genes, as well in patients with squamous cell carcinomas and EGFR amplification." (PMID 39062539, 2024). "The EGFR mutation rate was increased in patients with adenocarcinoma compared with that in patient with squamous carcinoma, and in non-smoking patients compared with that in smoking patients, and the differences were statistically significant (p<0.05)." (PMID 39634906, 2024). "Squamous cell carcinomas (including HNSCC, ESCC, and LSCC) are unique cancers, primarily driven by copy number gains and losses, rather than drivers with gain-of-function mutations such as KRAS and EGFR." (PMID 39605563, 2024).